IRF8 (interferon regulatory factor 8)
Diseases named in the same sentence as IRF8 in open-access papers (continued):
Sharing a sentence is not in itself a finding about the gene and the disease.
infection (continued). "By positional cloning, we determined that susceptibility to infection in BXH2 is caused by a mutation (R294C) in the interferon regulatory factor 8 (IRF8) (Ensembl:ENSMUSG00000041515)." (PMID 21731497, 2011). "The reduction of IRF8 expression in plasmacytoid dendritic cells could be associated with the development of serious infections in dialysis patients during the one-year follow-up." (PMID 37508555, 2023). "The deficit of IRF8 expression might be considered a potential risk factor triggering severe infections under dialysis conditions." (PMID 37508555, 2023). "Therefore, IRF8 mutant macrophages were described to be susceptible to ex vivo infections with intracellular bacteria." (PMID 37508555, 2023). "IRF8 is also a vital regulator of the immune response to various pathogenic infections." (PMID 37593742, 2023). "Furthermore, the transcription factor IRF8, significantly associated with the pathogenic infection and host response, was determined to mediate the upregulation of numerous genes relevant to PEDV infections." (PMID 35762780, 2022). "Thus, IRF8-deficient macrophages are susceptible to ex vivo infection with Mycobacterium bovis, Salmonella typhimurium, and Legionella pneumophila." (PMID 34067819, 2021). "Lymphocyte development and function in the setting of IRF8 deficiency can be altered through both direct cell-intrinsic effects and indirect effects because of defective hematopoiesis and external influences, such as infection." (PMID 29128673, 2018). "Previous experiments also suggest this rate of germination may be an underestimate for CEA10 infection since this fungus is cleared so effectively in irf8-/- macrophage-deficient conditions." (PMID 30071103, 2018). "In fact, the percentage of larvae with hyphae present was higher in irf8-/- macrophage-deficient hosts compared to wild-type hosts after infection with either an Af293-derived or a CEA10-derived strain, suggesting that the presence of macrophages inhibits A. fumigatus germination." (PMID 30071103, 2018). "Biallelic IRF8 deficiencies present at a young age with susceptibility to infection and myeloproliferation, similar to the IRF8-knock-out mouse, whereas mono-allelic IRF8 mutation was identified in an adult cohort with mycobacterial disease and represents a more subtle hypomorphic phenotype." (PMID 27755182, 2016). "As a consequence, IRF-8−/− mice were found to be extremely susceptible to aerosol infection with low-dose Mtb Erdman strain, succumbing to fatal acute TB within day 40 p.i., whereas the immunocompetent animals contained the infection switching from acute to chronic TB." (PMID 23717393, 2013). "Hence, IRF-8 loss-of-function is detrimental in restricting bacterial replication following aerogenous infection suggesting its causative role in lung pathogenesis occurring at late stages after Mtb entry." (PMID 23717393, 2013). "In lungs of IRF-8−/−, uncontrolled growth of pulmonary granulomas and impaired development of LS were observed, associated with unbalanced homeostatic chemokines, progressive loss of infiltrating T lymphocytes and massive prevalence of neutrophils at late infection stages." (PMID 23717393, 2013). "Taken into account these observations, we hypothesize that the presence of TNFR1-609(G/T) promoter polymorphisms can modify the binding affinity to ICSBP/IRF-8 and, therefore, it could be used to predict susceptibility to infection and to facilitate risk stratification of hematological patients." (PMID 21059262, 2010). "In contrast, in the current study with LmCen–/– infection, the expression of both IRF1 and IRF8 showed more reduction than LmWT infection." (PMID 39702382, 2024). "The reduction in antioxidant enzyme activity and intracellular lipid peroxidation further indicates that high expression of IRF8 is beneficial for maintaining the redox homeostasis of the organism during pathogen infection." (PMID 37593742, 2023).
infection (continued). "Among the hits, EED, a core subunit of PRC2, has been reported to repress lytic gene expression during KSHV de novo infection; IRF8 positively regulates STING-mediated innate immune responses to inhibit HSV-1 replication." (PMID 37010434, 2023). "As a main finding of the current work, we identified that dialysis patients with low levels of IRF8 expression in pDC developed more frequently and earlier serious infections during the one-year follow-up after the FACS analysis." (PMID 37508555, 2023). "IRF8 partners with various interferon regulatory factors, exerting broad regulatory effects in the stimulation of myeloid cells and immune responses to infections." (PMID 37508555, 2023). "Our data, which demonstrate that dialysis patients with low IRF8 expression are prone to severe infections, support the central role of IRF8 in protecting against infections." (PMID 37508555, 2023). "N protein was also expressed in IPEC-J2 infected with PEDV and mRNA expression levels of IRF8 were significantly upregulated 48 h PEDV post-infection (hpi) in IPEC-J2." (PMID 37593742, 2023). "In keeping with these data, we identified the transcription factors (TF) Stat2, Irf9 and Irf8 to be upregulated in NK cells infected with VACV, these TFs are associated with NK maturation and proliferation in response to infection." (PMID 36911702, 2023). "Mechanistically, TBX2-dependent innate IFN-γ is essential in T. gondii infection T-bet to produce IFN-γ, which is essential for host resistance to intracellular infection by maintaining IRF8 inflammatory dendritic cells at the infection site." (PMID 37593762, 2023). "An area under the receiver-operating-characteristics curve (AUROC) of 0.66 shows a useful discriminative capacity for the occurrence of infections through IRF8 expression." (PMID 37508555, 2023). "Plaque assays confirmed that Irf8-deficiency resulted in increased HSV-1 titers in the lungs and livers from Irf8‒/‒ mice compared with wild-type controls 72 h after infection." (PMID 35973990, 2022). "IRF8 also plays a key role in regulating Th1 polarization of early immune response following infection." (PMID 36078039, 2022). "IRF8 therefore is not only a key regulator of host response to infection, but is also a key regulator in host cancer immune surveillance and response to immunotherapy." (PMID 36078039, 2022). "For example, irf8-/- larval zebrafish that lack macrophages and have an excess of neutrophils clear infections with a fast-germinating CEA10 strain of A. fumigatus at a higher rate than wild-type larvae." (PMID 35333905, 2022). "Some interferon regulatory factors (irf1, irf3, irf4b, irf5, irf6, irf8) continued to show upregulation during the later stages of infection (day 6 to day 10) in virus-infected fish spleens." (PMID 36016951, 2022). "The expression heatmaps of the endothelial cell genes in the sample revealed that DCN and IFN-activated endothelial cell marker genes (Irf8, Rsad2, Ifit1, Ifit3, Iigp1) were significantly upregulated at 1 month post-infection as compared with the WT group." (PMID 36569953, 2022). "Similar to infection with Af293-derived strains, CEA10-infected larvae also succumb to the infection at a higher rate in the presence of indomethacin both in irf8+/+/irf8+/- and irf8-/- backgrounds." (PMID 35333905, 2022). "This study defines the critical function of early T-bet-dependent IFN-γ in sustaining inflammatory IRF8+ DCs during intracellular pathogen infection." (PMID 33465134, 2021). "As the principal regulator of HSCs both during homeostasis and under infection stress, IFNγ can strongly promote HSCs proliferation and increase the proportion of Sca‐1‐positive cells in WT and Irf8−/− LKs ex vivo." (PMID 34365741, 2021). "When we looked at different IRFs, we found that Irf7, Irf8, Irf5, and Irf4 were significantly upregulated in WT mouse brains upon infection with JEV." (PMID 34379515, 2021).
infection (continued). "Our data has identified that early ILC1-derived IFN-γ is critical for maintaining IRF8+ DCs during infection and limiting parasite replication throughout the host." (PMID 33465134, 2021). "Irf1, Irf7, Irf8, and Irf9 transcripts were significantly induced by infection in Ifnar1-/- mice, whereas Irf6 transcripts (abundant in uninfected mice) were significantly down-regulated." (PMID 34591933, 2021). "We found that within the first 3 h of infection, the neutrophils of cyba/irf8 double knockdown embryos are significantly less proficient in killing the internalized bacteria than the irf8-only knockdown embryos." (PMID 32174246, 2021). "Our data identifies that T-bet dependent production of IFN-γ by ILC1 and NK cells is indispensable for host resistance against intracellular infection via maintaining IRF8+ inflammatory DCs at the site of infection." (PMID 33465134, 2021). "We have used an experimental model of murine encephalitis induced by infection with JEV to investigate the role of IRF8 in pathological inflammation." (PMID 34379515, 2021). "In line, Irf8−/− mice showed elevated levels of HSV-1 DNA as well as increased production of viral particles after infection with HSV-1." (PMID 32165633, 2020). "We quantified the number of neutrophils recruited to the infection site, finding significantly more recruitment in irf8-/- larvae infected with an CEA10-derived strain compared to an Af293-derived strain." (PMID 30071103, 2018). "The numbers of CD4+CD25+Foxp3+ T cells were similar in naïve B6 and Irf8-/- mice, but this population expanded early during infection in both B6 and Irf8-/- mice." (PMID 28968468, 2017). "During infection, IRF-8 is induced in antigen presenting cells (APC) by IFN-γ and TLR ligands, binds to IRF-4, and stimulates IL-12 as well as IL-18 secretion, resulting in CD4+ Th1 cell differentiation and elimination of intracellular pathogens." (PMID 28968468, 2017). "Two weeks after re-infection of anthelmintic-treated mice, Irf8-/- as well as BXH-2 mice had significantly more adult worms in the small intestine than B6 mice." (PMID 28968468, 2017). "Irf8 expression was significantly down-regulated in MDSC from Hpb-infected compared to naïve B6 mice during primary infection." (PMID 28968468, 2017). "Like Irf8-/- mice, BXH-2 mice are highly susceptible to infections with intracellular pathogens including M. bovis (BCG), Salmonella enterica serovar Typhimurium, and Plasmodium chabaudi AS as well as M. tuberculosis." (PMID 28968468, 2017). "We performed a kinetic analysis of Th2 versus Tregs in B6 compared to Irf8-/- mice during infection." (PMID 28968468, 2017). "In contrast, infection of CD4+ T cells with IRF8-expressing retrovirus enhanced Th9 cell differentiation as demonstrated by increased production of IL-9 mRNA and protein without inducing transdifferentiation." (PMID 29233972, 2017). "Infection with FV1 lpg1− resulted in a reduction of IRF8 that is restored following infection with the FV1 lpg1− add back strain." (PMID 26630499, 2015). "It is possible that infection with FV1 lpg1− reduces the amount of IRF8, which in turn inhibits the capacity of other transcription factors, such as IRF1, to form heterodimeric complexes that bind the IL12B promoter." (PMID 26630499, 2015). "In this study, IRF-8 deficient mice (IRF-8−/−) were aerogenously infected with a low-dose Mtb Erdman virulent strain and the course of infection was compared with that induced in wild-type (WT-B6) counterparts." (PMID 23717393, 2013). "We found that the severe loss of Irf8 function in BXH2 mice completely protects against this pathology, preventing the development of neurological symptoms and prolonging survival post-infection." (PMID 23853600, 2013). "To identify IRF8-bound genes associated with ECM neuropathology, we queried the list of all genes whose expression is regulated by infection in Irf8-competent B6 mice for the presence of IRF8 binding sites (pair-wise comparison of B6 d7/d0)." (PMID 23853600, 2013).
infection (continued). "Up to day 15 post infection (p.i.)the two groups of mice exhibited comparable Mtb replication, with bacterial loads reaching similar levels in WT-B6 and IRF-8−/− spleens and lungs." (PMID 23717393, 2013). "This identified a total of 107 genes (123 probes; fold change ≥2, padj<0.05) that were strongly regulated by infection in an Irf8-dependent fashion (padj-interaction <0.05)." (PMID 23853600, 2013). "Genes increased by infection were strongly enriched for IRF8 binding sites, suggesting that IRF8 acts as a transcriptional activator in inflammatory programs." (PMID 23853600, 2013). "We also noted that during infection, the ECM-protective effect of the Irf8 mutation is phenotypically expressed in the lymphoid compartment of BXH2 and [BXH2×B6]F1." (PMID 23853600, 2013). "The overwhelming majority (80%) of genes increased during both infections contained at least one IRF8 binding site, again highlighting IRF8 as having a central role during inflammation and host response to infections." (PMID 23853600, 2013). "During infection, IRF8 activates antimicrobial defenses in myeloid cells, propagates pro-inflammatory signals and is required to amplify early immune responses by these cells." (PMID 23853600, 2013). "In this study we have extended these observations by dissecting the immune components occurring in lungs of IRF-8−/− mice following Mtb aerogenic infection." (PMID 23717393, 2013). "In vivo imaging revealed that as infection progresses, more lesions are formed in irf8 knock-down larvae than those observed in their wild-type siblings." (PMID 22694745, 2012). "In order to determine if, in neutrophil-enriched larvae, the capacity of the immunological bottleneck is increased during infection, irf8 knock-down larvae were injected with a mixture of Tet/Ery-resistant strains." (PMID 22694745, 2012). "Interestingly, the number of foci of infection increases associated with the rise in neutrophil levels upon irf8 knock-down, further suggesting that neutrophils carrying S. aureus cells indeed could be the ‘Trojan Horses’ facilitating overwhelming infection." (PMID 22694745, 2012). "We also investigated the relevance of IRF8 targets discovered by ChIP-chip, to host defenses against infections in vivo." (PMID 21731497, 2011). "The transcriptional and cellular pathways regulated by IRF8 and essential for resistance to infections were studied by a combination of genome-wide methods, including transcriptional profiling and chromatin immunoprecipitation (ChIP-chip)." (PMID 21731497, 2011). "In contrast, another patient with a different novel, de novo heterozygous IRF8 variant (c.10C>T) had milder early life infection susceptibility, but no lymphoproliferation, nor immune-mediated organ disease, and no prior exposure to BCG vaccine." (PMID 41229418, 2025). "On the other hand, IRF8-inducing differentiation of dendritic cells and type I interferon production by dendritic cells and monocytes play an essential role in the innate and adaptive immune response to infections." (PMID 37508555, 2023). "Dialysis patients with low IRF8 expression in pDC, lying below the median, tended to develop earlier and more frequent infections leading to hospital admissions during the one-year follow-up period (68% IRF8 expression below the median vs. 76% IRF8 expression above the median)." (PMID 37508555, 2023). "Studies with larger cohorts are required to determine whether IRF8-positive cell proportions or IRF8 expression on different immune cells could serve as suitable parameters for predicting infection events." (PMID 37508555, 2023). "In our data, IRF8 was upregulated only in the PEDV 85-7C40 infection process and thus was speculated to mediate the immune regulatory process between PEDV strain 85-7C40 and host cells." (PMID 35762780, 2022).
infection (continued). "As expected, the infection of irf8 knockdown embryos led to a higher percentage of infected neutrophils and a higher average number of bacteria per infected neutrophil when compared to control embryos, which facilitated the observation of S. aureus-infected neutrophils." (PMID 32174246, 2021). "On day 14 after primary or challenge infection, there were marked increases in the total cellularity of lymphoid tissues from B6 as well as IRF-8 deficient mice with significantly higher cell numbers in the MLN and spleen of Irf8-/- compared to B6 mice." (PMID 28968468, 2017). "Of these, IRF4 expression increased but IRF8 expression decreased during infection." (PMID 25658110, 2015). "The distinct expression phenotypes exhibited by IRF1 and IRF8 following infection with FV1 lpg1− may be due to the difference in regulation of these two transcription factors." (PMID 26630499, 2015). "However, at late stages of infection, when IRF-8−/− granulomas become acute exhibiting features of caseous necrosis, the influx of selected immune cells declined, causing failure of granuloma contain mycobacterial dissemination." (PMID 23717393, 2013). "Loss-of-function mutation in the mouse IRF-8 gene may impair the induction of type I IFN, which result in rapid dissemination of the infection of mycobacterium TB and rapid necrosis of infected tissues." (PMID 22879909, 2012). "In addition, enhanced mortality and increased numbers of foci of infection in neutrophil-enriched (irf8 knock-down) infected larvae, also suggesting that neutrophils form the immunological checkpoint for progression to an overwhelming infection." (PMID 22694745, 2012). "Subsequently, we assessed whether the regulator of IFN-β transcription was IFN-inducible, as has been suggested for IRF-8 in the context of infection by MCMV or paramyxovirus." (PMID 19798431, 2009). "In addition, mice lacking IRF8 were shown to have dramatically increased susceptibility to infections." (PMID 37508555, 2023). "Analysis of these IRF8 target genes in Mycobacterium tuberculosis-infected lungs revealed specific enrichment of pathways/genes in antigen processing and presenting, indicating a key role of IRF8 function in myeloid cells in regulating early response to infection." (PMID 36078039, 2022). "Therefore, we hypothesized that conditionally deleting IRF8 expression by DCs would result in uncontrolled parasite replication during infection and rapid host mortality." (PMID 33465134, 2021). "Indeed, IRF-8 is essential for controlling infection in both mice and humans." (PMID 31849969, 2019). "Unlike Rac2 D57N larvae, Irf8 morphants also had increased susceptibility to cpsA infection, supporting the importance of macrophages for controlling S. iniae infection and suggesting that neutrophils and macrophages perform non-redundant functions in host defense against S. iniae." (PMID 28658259, 2017). "Through its IRF-8 association domain (IAD), IRF-8 interacts with other transcription factors, such as PU-1, IRF-1, IRF-4, and IRF-2, and plays an important role in immunity against tumors and infections with intracellular pathogens, including bacteria, viruses, and protozoan parasites." (PMID 28968468, 2017). "Therefore, it is possible that the reduction in TNF expression observed during FV1 lpg1− infection may also be IRF8-specific." (PMID 26630499, 2015). "Thus, at early stage of infection high levels of CCL19 in IRF-8−/− mice may account for the pulmonary recruitment of immune infiltrates, possible through a chemokine/lymphotoxin loop." (PMID 23717393, 2013). "However, this experiment could be confounded by the fact that in the neutrophil-enriched irf8 morphant larvae, more individual foci of infection might occur." (PMID 22694745, 2012).